BCL2 (BCL2 apoptosis regulator)
Diseases named in the same sentence as BCL2 in open-access papers (continued):
Sharing a sentence is not in itself a finding about the gene and the disease.
non-small cell lung carcinoma (146 papers, 1995 to 2025). A group of at least three distinct histological types of lung cancer, including non-small cell squamous cell carcinoma, adenocarcinoma, and large cell carcinoma. "In a study conducted in India, a variant of the BCL2 gene (rs2279115) was found to contribute to the risk of developing non-small cell lung cancer." (PMID 37886944, 2023). "For example, breast-, colorectal-, non-small cell lung-cancer patients with high expression of the anti-apoptotic protein BCL-2 are associated with favorable prognoses." (PMID 34968392, 2021). "It has been shown that chrysin caused non-small cell lung cancer A549 to undergo apoptosis via the increase of the Bax/Bcl-2 ratio and activation of caspase-3 and −9." (PMID 28320429, 2017). "Positive bcl-2 expression was found to be significantly associated with enhanced docetaxel sensitivity in vitro in non-small cell lung cancer." (PMID 17430582, 2007). "It has been reported that phosphorylated paxillin increases Bcl-2 expression through the ERK signaling pathway as the cause of cisplatin resistance in non-small cell lung cancer, and Src or ERK inhibitors help restore the sensitivity of lung cancer patients to cisplatin chemotherapy." (PMID 37175948, 2023). "For this reason, the goal of our study is examined the expression of VEGF and Bcl-2 in unresectable non-small cell lung cancer, the association of the expression with the pathohistological characteristics of the tumor as well as the correlation with the clinical parameters of the examined patients." (PMID 36766867, 2023). "Beclin1 protein deficiency has also been observed inkidney cancer, non-small cell lung cancer, and cholangiocarcinoma.Hyperexpression of the gene encoding Bcl-2, which can form a complex withBeclin1 (Beclin1/Bcl-2) inhibiting autophagy, has been observed in variouslymphomas." (PMID 37908768, 2023). "Similarly, a recent study showed that downregulation of Bcl-2 was associated with p16-mediated apoptosis in non-small-cell lung cancer cells." (PMID 32060352, 2020). "Indeed, miR-30a overexpression is associated with reduced BCL-2 expression in non-small-cell lung cancer, leading to the increased apoptotic death of these cells." (PMID 32309442, 2020). "Moreover, treatment with waltonitone in non-small cell lung cancer led to an upregulation of miR-663, which further caused downregulation of bcl-2 and induces cancer cell apoptosis." (PMID 27667893, 2016). "For example, in a systematic review of studies of Bcl2 in non-small-cell lung cancer, almost all the smaller studies showed a statistically significant relationship between Bcl2 and the risk of dying, whereas the three large studies were all nonsignificant and showed a much smaller effect." (PMID 19367280, 2009). "In a dose- and time-dependent manner, GA suppressed the growth and induction of non-small cell lung carcinoma (NSCLC) A549 cell line, which was linked to downregulated B-cell lymphoma 2 (Bcl-2) and increased (Bcl-2)-associated X protein (Bax)." (PMID 40427522, 2025). "Elevated levels of lncRNA GHRLOS significantly inhibited cancer cell proliferation and invasion while promoting apoptosis through the modulation of E-cadherin, N-cadherin, BAX, and Bcl-2 expression in non-small-cell lung cancer." (PMID 39940682, 2025). "Gefitinib and ginsenoside Rg3 together dramatically boost apoptosis in non-small cell lung cancer cells by upregulating the pro-apoptotic protein Bax and caspase-3 activity while downregulating the anti-apoptotic protein Bcl-2." (PMID 40728967, 2025). "The caffeic acid exposure also increased the expression of the anti-apoptotic proteins survivin and Bcl-2 in another non-small-cell lung cancer cell line, A549." (PMID 39338293, 2024). "In this study, we first found that the BCL-2 inhibitor APG-2575 enhanced the potent antitumor effects of ICIs on non-small cell lung cancer through its previously unreported ability to augment immune responses." (PMID 38062129, 2024).
non-small cell lung carcinoma (continued). "XBS improves Bcl-2 and Beclin-1 communication, making it an effective treatment for gefitinib-resistant non-small cell lung cancer (NSCLC)." (PMID 39650649, 2024). "On the other hand, knockdown of ARID1A upregulates the expression of cycle-related proteins cyclinD1 and Bcl-2 and inhibits cell apoptosis in non-small cell lung cancer (NSCLC)." (PMID 34671561, 2021). "Because Bcl-2 inhibitors bind to Mcl-1 with low affinity, Mcl-1 overexpression confers acquired resistance to Bcl-2 inhibitors in multiple cancer types, including non-small cell lung cancer (NSCLC) and acute myeloid leukemia." (PMID 32587776, 2020). "BCl2 has been documented as a miR-30a target in various cancers, including non-small cell lung carcinoma, renal carcinoma, cutaneous squamous cell carcinoma." (PMID 32499869, 2020). "Studies have indicated that miR-30a-5p enhanced paclitaxel sensitivity in non-small cell lung cancer by inducing apoptosis through Bcl-2 inhibition, and miR-30a expression negatively correlated with Bcl-2." (PMID 32161548, 2020). "Previous studies have shown that benzimidazole anthelmintics potentiate the cytotoxicity of BH3 mimetic ABT-263 (a BCL2/BCL2L1 inhibitor) on non-small cell lung cancer." (PMID 32486166, 2020). "XIST has been shown to be oncogenic in non-small cell lung cancer, where it increases Bcl-2 levels by functioning like a sponge for miR-449a, which then down-regulates Bcl-2." (PMID 30555629, 2018). "miRNA-1290 promotes asiatic acid induced apoptosis by decreasing BCL2 protein level in A549 non small cell lung carcinoma cells." (PMID 32309578, 2016). "It has also been demonstrated in non-small cell lung cancer cell lines (NSCLC) that EGFR-TKIs exert their cytotoxic effects through inhibition of the apoptosis-related protein BCL2." (PMID 27655662, 2016). "In a preclinical study, reported that cryptophycin-52 induced in vitro Bcl-2 hyperphosphorylation, cell cycle arrest and growth inhibition in human non-small cell lung carcinoma cells." (PMID 26132844, 2015). "This study investigated the association of BCL2-938C>A(rs2279115) and BAX-248G>A(rs4645878) promoter region SNPs and the clinical responses and outcomes of 235 non-small cell lung cancer (NSCLC) patients treated with platinum-based chemotherapy." (PMID 26656462, 2015). "Molecularly, ARTN stimulates survival and anchorage-independent growth of human non-small cell lung cancer cells by upregulating BCL-2 expression." (PMID 25120606, 2014). "In non-small cell lung cancer, anti-apoptotic Bcl-2 protein expression was higher in squamous cell carcinomas when compared to adenocarcinomas." (PMID 24688727, 2013). "Xiong and his colleagues found that microRNA-7 inhibited the growth of human non-small cell lung cancer A549 cells through targeting BCL-2." (PMID 23151088, 2012). "This was evidenced by the dose-dependent increase of apoptotic markers such as of caspase-3 and the Bax/Bcl-2 ratio and is in line with the finding that curcumin downregulates Bcl-2 in non-small cell lung cancer cells." (PMID 22126332, 2011). "A recent systematic review of the literature showed that over-expression of Bcl-2 was a good prognostic factor for survival in patients with non-small cell lung cancer." (PMID 20403207, 2010).
non-small cell lung carcinoma (continued). "Patients with non-small-cell lung carcinomas (n = 27) in which > 50% of the tumour cells were bcl-2 positive showed a survival advantage compared with those with 0-25% bcl-2-positive cells (P = 0.02)." (PMID 7599047, 1995). "Vitexin, found in the traditional Chinese herb Crataegus pinnatifida (hawthorn), has been shown to induce apoptosis through the mitochondrial pathway by lowering the Bcl-2/Bax ratio and increasing the expression of cleaved caspase-3 in human non-small cell lung cancer A549 cells." (PMID 40283879, 2025). "According to the PASS predictions, prodigiosin had a high probability (Pa > 0.5) of exhibiting various anticancer activities, including an apoptosis agonist (Pa = 0.723), antineoplastic (non-small cell lung cancer, Pa = 0.549; solid tumors, Pa = 0.428; and others), and bcl2 antagonist (Pa = 0.310)." (PMID 39587466, 2024). "Its antitumor ability is hundreds of times stronger than that of existing antitumor drugs.Cryptophycin-52 not only has microtubule inhibition activity but also showed the ability to induce apoptosis by Bcl-2 phosphorylation in the human H460 non-small-cell lung carcinoma (NSCLC) cell line." (PMID 38004647, 2023). "IRF7 activated a positive feedback regulatory loop of interferon signaling and subsequently activated the RIG-I-like receptor signaling pathway and BCL-2 expression to inhibit apoptosis and promote proliferation, invasion and migration of non-small cell lung cancer cells." (PMID 37251373, 2023). "In addition, overexpression of miR-98 activates the Akt/bcl2/Bax signaling axis to induce apoptosis and improve patient prognostic indicators in non-small-cell lung cancer (NSCLC)." (PMID 35805066, 2022). "Overexpression of BTG1 inhibited the proliferation, migration and invasion of hepatocytes, thyroid, nasopharynx, esophagus, breast and non-small cell lung cancer cells and induced apoptosis and cell cycle arrest by downregulating the expression of Cyclin D1, Bcl-2 and MMP-9." (PMID 36339000, 2022). "c, lower the rate of Bcl-2, and suppress the proliferation of non-small cell lung cancer." (PMID 36286449, 2022). "Similarly, it has been found that vitexin induced apoptotic activity and decreased Bcl-2/Bax expression ratio while increased the expression of cleaved caspase-3 in human non-small cell lung cancer A549 cells." (PMID 34768743, 2021). "Also, in non-small cell lung cancers, miR-34a was identified to play a role in apoptosis by targeting BCL2." (PMID 32365562, 2020). "We also confirmed the role of bcl-2 on TAM functions in non-small cell lung cancer histotype." (PMID 32269145, 2020). "The elevated expression of RRM2 may lead to the poor prognosis for patients with non-small cell lung cancer by stabilization of Bcl-2, which is a critical regulator of apoptosis." (PMID 31043166, 2019). "Secondly, PANDAR has been shown to promote cell survival in non-small cell lung carcinoma (NSCLC) in which low expression level of PANDAR permits NF-YA to up-regulate Bcl2 expression, an anti-apoptotic gene." (PMID 32106407, 2020). "For instance, it has been reported that lncRNA BANCR enhances the level of apoptosis in NSCLC (non-small cell lung carcinoma) cell lines in vivo by modulating the expression of Bcl-2 and BAX." (PMID 32499679, 2020).
non-small cell lung carcinoma (continued). "Cryptophycin-52 induced apoptosis, which is confirmed through the hyperphosphorylation of Bcl-2, cell cycle arrest, and growth inhibition in preclinical trials for the in vitro human non-small cell lung carcinoma (NSCLC) cell line." (PMID 29558431, 2018). "Knockdown of ARID1A in non-small cell lung cancer (NSCLC) resulted in up-regulation of the expression of cycle-related proteins cyclinD1 and Bcl-2 and inhibition of apoptosis." (PMID 39697230, 2024). "In order to generalize these results, the modulation of selected genes from Hippo pathway after Bcl-2 silencing was also determined in human breast adenocarcinoma, MDA-MB-231, and human non-small cell lung cancer, H460, cell lines." (PMID 38755629, 2024). "In non-small-cell lung cancer (NSCLC) cell experiments, cardamonin triggered apoptosis by activating caspase-3, increasing Bax levels, and decreasing Bcl-2 levels." (PMID 39334932, 2024). "In a study on non-small cell lung cancer, PGRN was found to promote the expression of the antiapoptotic protein Bcl-2 by activating the PI3K-AKT signaling pathway." (PMID 39337417, 2024). "A previous study reported that quercetin could downregulate IL-6, STAT-3, Bcl2 activity, NF-kB expression, and upregulate the Annexin and the PI cell population through induction of mitochondrial-mediated apoptosis in A549 cells in non-small-cell lung cancer (NSCLC)." (PMID 36926328, 2023). "Particularly, as shown in human non-small cell carcinoma cell lines, CISD2/NAF-1 interacts with the anti-apoptotic protein B-Cell CLL/Lymphoma 2 (BCL2) and this interaction is required for the BCL2–dependent inhibition of the autophagosome initiating complex." (PMID 36774344, 2023). "In non-small cell lung cancer cells, PXN activated ERK and increased the binding of CREB to the Bcl-2 promoter, elevating the Bcl-2 expression level and reducing cellular apoptosis." (PMID 36923874, 2023). "Fisetin treatment of plasma cancer cells (U266) and human non-small cell lung cancer cell lines (NCI-H460) promoted the activation of caspase-3, upregulated Bax, Bim and Bad proteins expression while down-regulated Mcl-1L and Bcl-2 expression." (PMID 34768743, 2021). "This study aimed to evaluate the role of serum miR-148a as a non-invasive biomarker in non-small cell lung cancer (NSCLC) patients and to assess the correlation between miR-148a and Bcl-2, as one of its target proteins." (PMID 34181356, 2021). "In non-small-cell lung cancer (NSCLC) A549 and H460 cells, cardamonin activated caspase-3, increased Bax levels, decreased Bcl-2 levels, thus inducing apoptosis." (PMID 36046386, 2020). "These aptamers significantly suppress the growth of human non-small cell lung cancer (NSCLC) tumors in vivo by selectively inhibiting the activation of Stat3 and its downstream proteins such as Bcl-2, Bcl-xL, Mcl-1, survivin, VEGF, Cyclin D1, and c-myc." (PMID 31640176, 2019). "As an example, one study in non-small lung cell cancers showed that drug-resistant tumor cells with acquired resistance conferred by the EGFRT790M mutation could be re-sensitized to EGFR TKIs by co-targeting them with navitoclax, an inhibitor of BCL-2 and BCL-XL." (PMID 31921698, 2019). "AEG-1/MTDH is also crucial in the carcinogenesis of non-small cell lung cancer (NSCLC) and inhibits apoptosis by enhancing the level of the antiapoptotic protein, Bcl-2, and activating the PI3K/Akt pathway." (PMID 25009642, 2014). "The pro-apoptotic Bcl-2 protein BAD initiated apoptosis in human cells and has been identified as a prognostic marker in non-small cell lung cancer (NSCLC)." (PMID 23725574, 2013).
non-small cell lung carcinoma (continued). "In non-small cell lung cancer, SSD and GEFITINIB are combined to reduce the expressions of P-Stat3 and BCL2, indicating that SSD can inhibit the activation of the P-Stat3/BCL2 signaling pathway induced by gefitinib and inhibit the resistance of gefitinib in cancer." (PMID 37489008, 2023). "BDA-366 negatively regulates the activity but not the expression of Bcl-2 in H460 non-small cell lung cancer cells." (PMID 37237269, 2023). "Sanguinarine inhibits cell proliferation and induces apoptosis by down-regulating JAK/STAT signaling pathway in non-small cell lung cancer, silencing STAT3 expression in non-small cell lung cancer, and further increasing Bax/Bcl-2 to promote cysteine The activity of winter enzyme can inhibit tumor." (PMID 36686745, 2022). "Furthermore, curcumin inhibited the cell proliferation of laryngeal cancer cells via miR15a by targeting Bcl2 and PI3K/Akt and induced apoptosis via the upregulation of miR192-5p by suppressing PI3K/Akt in human non-small cell lung cancer cells." (PMID 30534000, 2018). "The results of the molecular docking simulation above showed that BCL2 tended to be the potential target involved in EGFR-TKI resistance and non-small cell lung cancer pathways and LCA could be an active compound to decrease the EGFR-TKI resistance." (PMID 30400936, 2018). "Novel targets such as Bcl-2, VEGF, and delta-like protein 3 (DLL3) are currently being investigated in small cell lung cancer, which, if successful, may be applied to non-small-cell lung cancers." (PMID 26823665, 2015). "Perillyl alcohol inhibited the proliferation of human non-small cell lung cancer cells (A549 and H520) with IC50 values greater than 1 mM, inducing cell cycle arrest and apoptosis with increases in the expression of Bcl2, bax and p21 and in the caspase-3 activity." (PMID 25101672, 2014). "Cancer cell models commonly harbour constitutively expressed BAK and multiple PBPs (these may include BCL-2, BCL-XL, MCL-1, A1 and BCL-W coexpression in the case of non-small cell lung cancer – data unshown)." (PMID 18725943, 2008). "Moreover, phloretin was shown to induce apoptosis of non-small-cell lung cancer (NSCLC) cell line A549, Calu-1, H838, and H520 (IC50 approx. from 50 to 100 μM) through deregulation of Bcl-2 and other ROS-related pathways, such as P38 MAPK and JNK1/2 which are related to the rise of ROS." (PMID 29618945, 2018). "Covering a broad spectrum of solid tumors, Non-Small-Cell Lung Cancer (NSCLC), Head and Neck Squamous Cell Carcinoma (HNSCC) and synovial sarcoma cell lines were exposed to fractionated radiation as standard therapy with or without Bcl-2 protein inhibition." (PMID 35887198, 2022).